HOTAIR (HOX transcript antisense RNA)
Diseases named in the same sentence as HOTAIR in open-access papers (continued):
Sharing a sentence is not in itself a finding about the gene and the disease.
colorectal cancer (continued). "Moreover, it has been shown that HOTAIR is highly expressed in the 5FU drug resistant colorectal cancer cells." (PMID 32245498, 2020). "In colorectal cancer, HOTAIR upregulated ATG12 expression by sponging miR-93." (PMID 33050642, 2020). "Pathway analysis using IPA revealed relatively few significant pathways including HOTAIR regulatory pathway (Z-score = 1.134), colorectal cancer metastasis signaling (Z-score = 0.378), neuroinflammation signaling pathway (Z-score = −1.134), and glioblastoma multiforme signaling (Z-score = −0.447)." (PMID 32636844, 2020). "Likewise, SLCO4A-AS1 and HOTAIR were found to be overexpressed in colorectal cancers, and acted as oncogenes in in vitro and in vivo studies." (PMID 33050642, 2020). "In addition, the knockdown of HOTAIR helps increase colorectal cancer cells sensitivity to cisplatin." (PMID 35582574, 2019). "HOTAIR is shown to be upregulated in colorectal cancer tissue vs. normal adjacent tissue." (PMID 35582574, 2019). "Significantly high expression of HOTAIR has been indicated in breast cancer, pancreatic cancer, liver cancer, colorectal cancer, lung cancer, and other malignant tumors, and with which tumor cells invasion and metastasis, tumor recurrence, and poor prognosis are closely related." (PMID 29463216, 2018). "Examples include HOTAIR in colorectal cancer and MALAT1 in non-small cell lung cancer." (PMID 25428914, 2015). "Also, enforced HOTAIR expression has been found in other tumors, including pancreatic cancer, colorectal cancer, hepatocellular carcinoma, and gastrointestinal stromal tumors." (PMID 24155936, 2013). "Thus we focused on HOTAIR because many investigators have reported that HOTAIR has an oncogenic function in several other cancers (breast, liver, pancreas, colorectal cancers and laryngeal squamous cell carcinoma)." (PMID 23936419, 2013). "Thus, the expression of HOTAIR correlates with metastasis and poor outcome in primary breast tumors, gastrointestinal, hepatocellular and colorectal cancers and the expression of MALAT correlates with survival in early-stage lung adenocarcinoma." (PMID 23887658, 2013). "Previous research has found that HOTAIR negatively regulates the expression of miRNAs primarily by functioning as a competing endogenous RNA (ceRNA) sponge (e.g., miR-34a and miR-218) to contribute to drug resistance in both gastric and colorectal cancer, respectively." (PMID 32462038, 2020). "Moreover, HOTAIR can promote colorectal cancer cell migration and invasiveness and may participate in epithelial-mesenchymal transition." (PMID 27148353, 2016). "Thus, HOTAIR is a valuable factor for colorectal cancer prognosis." (PMID 27148353, 2016). "For these reasons, HOTAIR or SUZ12 might be a treatment target in colorectal cancer." (PMID 25334066, 2014). "HOTAIR/miR-326/FUT6 axis modifies α1, 3-fucosylation of CD44, which triggers phosphatidylinositol 3 kinase (PI3K)/Akt/mTOR pathway mediating colorectal cancer progression." (PMID 35309939, 2022). "Knockdown of HOTAIR and ATG12, or overexpression of miR-93, suppressed autophagy and restored radiosensitivity in colorectal cancer cells." (PMID 33050642, 2020). "On the contrary, HOTAIR has been identified to be an oncogene in HCC, colorectal cancer, and chondrosarcoma." (PMID 33050642, 2020). "By analyzing the expression of 17 lncRNAs and 31 circRNAs in biopsies and serum exosomes from colorectal cancer (CRC) patients through qRT-PCR, we detected CCAT1, CCAT2, HOTAIR, and UCA1 upregulation and CDR1AS, MALAT1, and TUG1 downregulation in biopsies." (PMID 30195762, 2018). "HOTAIR and MALAT1 have also been demonstrated to be involved in breast and colorectal cancer metastasis." (PMID 25428914, 2015). "MALAT-1, HOTAIR, PVT-1 and CCAT1-L are up-regulated in colorectal cancer tissue while ncRAN is down-regulated." (PMID 25119862, 2014).
colorectal cancer (continued). "Furthermore, a correlation is shown to exist between the expression levels of HOTAIR and HIF1A in colorectal cancer cells (correlation coefficient 0.904, p ≤ 0.005) but this measurement is not observed in patients." (PMID 40072116, 2025). "For example, HOTAIR (HOX transcript antisense RNA), a lncRNA that is overexpressed in breast, liver, and colorectal cancers, has been shown to promote tumor growth, metastasis, and drug resistance through various mechanisms, including the epigenetic silencing of tumor suppressor genes." (PMID 37232821, 2023). "Additionally, the stemness of cancer cells in colorectal cancer can be regulated by lncRNA FARAS1, LINC00657, HOTAIR, and BCAR4." (PMID 35470736, 2022). "For example, HOTAIR is detected in colorectal cancer and represents an effective negative prognostic biomarker for colorectal cancer in blood samples." (PMID 29416704, 2018). "Similarly, HOTAIR also induces genome-wide PRC2 retargeting, participates in epigenetic regulation in colorectal cancer, and promotes metastases." (PMID 25334066, 2014). "These include but are not restricted to lncRNAs like HOTAIR, Pvt1, RoR, prostate cancer–associated transcript 1 (PCAT1), ANRIL, H19, nuclear enriched abundant transcript 1 (NEAT1), UCA1, lung adenocarcinoma transcript 1 (LUADT1), colorectal cancer–associated lncRNA (CCAL), and many more." (PMID 30296263, 2018).
hepatocellular carcinoma (94 papers, 2012 to 2025). A malignant tumor that arises from hepatocytes. "HOTAIR is also overexpressed in nasopharyngeal carcinoma, breast, pancreatic, liver, gastric and non-small cell lung cancer.HOTAIR was proven to be linked with MDSCs functions in hepatocellular carcinoma lines." (PMID 36817434, 2023). "A great deal of evidence has linked HOTAIR with various cancer types, including gastric, colorectal, hepatoma, and esophageal squamous cell carcinoma." (PMID 33809601, 2021). "Similarly, enhanced HOTAIR expression was found to be associated both with progression and tumor recurrence in hepatocellular carcinoma by regulating the Wnt/β-catenin signal transduction pathway." (PMID 31195674, 2019). "Furthermore, HOTAIR overexpression has been associated with hepatocellular carcinoma (HCC) progression and its reoccurrence after liver transplantation." (PMID 29685978, 2018). "In liver cancer (LC), circulating HOTAIR is a potential biomarker used for hepatocellular carcinoma (HCC) detection in cirrhotic livers and prediction of tumour stage (El-Shendidi, Ghazala and Hassouna, 2022)." (PMID 38887279, 2024). "HOTAIR, highly expressed and associated with poor prognosis in hepatocellular carcinoma, promoted the secretion of CCL2 in hepatocellular carcinoma cells and increased the proportion of macrophages and MDSCs." (PMID 36831498, 2023). "The suppression of miR-122 by HOTAIR through DNA methylation resulted in the activation of Cyclin G1 and enhanced tumor growth in hepatocellular carcinoma (HCC)." (PMID 38132140, 2023). "LncRNA HOTAIR has been demonstrated to be overexpressed in hepatocellular carcinoma (HCC), also promoting autophagy in these cells by upregulating ATG3 and ATG7 at mRNA and protein levels." (PMID 35309939, 2022). "For instance, HOTAIR upregulates DNA methyltransferases in hepatocellular carcinoma to epigenetically suppressed miR-122." (PMID 36274134, 2022). "Patients with hepatocellular carcinoma whose HOTAIR and PLK1 expression increased more than twice, the expression of PRC2 target gene and EPCAM also increased significantly." (PMID 35093153, 2022). "HOTAIR negatively regulates miR-218 expression in hepatocellular carcinoma (HCC) cells through an EZH2-miR-218-2 promoter regulatory axis, and this functional interaction increases cell growth and proliferation." (PMID 33540611, 2021). "Our results suggest c-Met and HOTAIR axis as a modulator of epithelial/mesenchymal hybrid state in hepatocellular carcinoma cells." (PMID 32650779, 2020). "In conclusion, the function of HOTAIR in Taxol-resistance and its related potential mechanism in hepatocellular carcinoma were revealed." (PMID 32700738, 2020). "A study indicated that HOTAIR was higher in hepatocellular carcinoma tissues than that in adjacent normal tissues, and significantly associated with poor differentiation, metastasis, progression and prognosis." (PMID 32104724, 2020). "Via the HOTAIR/miR-130a-3p/HIF-1α axis, HOTAIR positively regulates HIF-1α expression resulting in enhanced glycolysis in hypoxic hepatocellular carcinoma cells." (PMID 32640630, 2020). "We conducted the present study to investigate a role of HOTAIR in Taxol-resistance of hepatocellular cancer cells: Taxol-resistant HepG2 and Taxol-resistant SMMC7721." (PMID 32700738, 2020). "The results showed that HOTAIR and its binding target miR-34a were unusually expressed in Taxol-resistant hepatoma cells." (PMID 32700738, 2020). "The expression of the long noncoding RNA HOTAIR (HOX Transcript Antisense Intergenic RNA) is largely deregulated in epithelial cancers and positively correlates with poor prognosis and progression of hepatocellular carcinoma and gastrointestinal cancers." (PMID 30154449, 2019). "Hepatoma cell lines with HOTAIR overexpression secreted higher CCL2 and this promotes TAM and MDSCs proliferation." (PMID 31072041, 2019).
hepatocellular carcinoma (continued). "It has been demonstrated that lncRNA HOTAIR binds with many miRNA including miR-130a, miR-218, miR-7, miR-203, etc. in gallbladder cancer, hepatocellular carcinoma, or renal cancer cells." (PMID 30429228, 2019). "Up-regulation of lncRNA HOTAIR was found in many other cancer tissues such as gallbladder cancer, pancreatic cancer, hepatocellular carcinoma, and nasopharyngeal carcinomas compared with their normal tissues." (PMID 30111807, 2018). "Many lncRNAs are expressed in a tissue- and cancer-type-restricted manner and have already been shown to be useful as prognostic markers, such as HOTAIR in breast tumors and hepatocellular carcinomas, MALAT1 in non-small cell lung cancer." (PMID 26895099, 2016). "Here, it has been demonstrated that CD90+ hepatocellular cancer cells derived from the Huh7 cell line secrete exosomes containing different types of lncRNAs, including HOTAIR, HULC, linc-ROR and H19." (PMID 26516918, 2015). "Knockdown of HOTAIR was associated with reduced expression of VEGF and MMP-9 in BEL7402 hepatocellular carcinoma cells." (PMID 25405331, 2015). "In liver cancer, HOTAIR is a prognostic factor of hepatoma metastases and relapse after hepatic resection or liver transplantation." (PMID 25334066, 2014). "The level of HOTAIR expression is higher in patients with lymph node metastasis in hepatocellular cancer." (PMID 23443164, 2013). "In addition, the lncDiseas database showed that HOTAIR was related to hepatocellular carcinoma diseases." (PMID 37880710, 2023). "HOTAIR regulates miR-130a-3p expression in hepatocellular carcinoma cells." (PMID 35619625, 2022). "However, the high expression of HOTAIR can promote the recurrence and metastasis of hepatocellular carcinoma, affect the prognosis of patients and shorten the survival time of patients." (PMID 35093153, 2022). "In addition, RAB35 was identified as a binding protein of lncRNA HOTAIR and its expression was positively regulated by RNA HOTAIR, accelerating the metastasis of hepatocellular carcinoma cancer cells." (PMID 34500436, 2021). "Expression of HOTAIR has been increased in hepatocellular carcinoma samples." (PMID 33123468, 2020). "In addition, using a differentiation model of PBMCs from human donors, cell lines of hepatocellular carcinoma overexpressing HOTAIR promoted MDSC differentiation in co-cultures." (PMID 31404149, 2019). "Recently, the mechanisms and functions of several lncRNAs, such as lncRNA-HEIH, HULC and HOTAIR, were uncovered in hepatic carcinoma, the most common hepatic malignancy, and these findings led to the deeper understanding of the regulation networks and thetumorigenesis in hepatic carcinoma." (PMID 30305026, 2018). "Intriguingly, HOTAIR could promote migration and invasion of hepatocellular carcinoma cells by inhibiting RBM38 and activating the Wnt/β-catenin signaling pathway." (PMID 26172293, 2015). "Notably, the lncRNAs HOTTIP, H19, HOTAIR, MALAT1, antisense Igf2r (AIR), HOXA13, GTL2 (also called MEG3) and uc002mb have been reported in association with hepatocellular carcinoma (HCC)." (PMID 26172293, 2015). "HOTAIR was also shown to be involved in hepatocellular carcinoma." (PMID 25954300, 2015). "HOTAIR may also serve as a potential biomarker for the lymph node metastasis of hepatocellular carcinoma." (PMID 25422887, 2014). "There is growing evidence that HOTAIR may have prometastasis activity in several cancer types, including breast, pancreatic, and hepatocellular carcinoma (HCC)." (PMID 23862139, 2013). "Besides, low-expressed HOTAIR suppressed cell invasion, enhanced Taxol-induced apoptosis, and inhibited Akt phosphorylation and Wnt/β-catenin signaling pathways by up-regulating miR-34a, so as to reverse Taxol-resistance in hepatoma cells." (PMID 32700738, 2020). "However, the possible association of AKT activation and HOTAIR in Taxol-resistance of hepatocellular carcinoma have not been investigated." (PMID 32700738, 2020).
hepatocellular carcinoma (continued). "HOTAIR transcription positively correlates with poor prognosis and progression in several epithelial tumors, including hepatocellular carcinoma (HCC) and gastrointestinal cancers." (PMID 30154449, 2019). "In hepatocellular carcinoma (HCC), HOTAIR was overexpressed in HCC tissues as compared with adjacent non-tumor tissues." (PMID 30266744, 2018). "HULC, MALAT-1, TUC338, TUC339, lncRNA-HEIH, MVIH, HOTAIR, lnc-RoR, and HOTTIP have all been associated with higher expression in hepatocellular carcinoma (HCC) compared with normal liver tissue, while MEG3 is repressed in HCC." (PMID 27007663, 2016). "A study investigated the relationship between the lncRNAs HOTTIP, H19, and HOTAIR and miRNA 152, as well as the role of these interactions in the progression of HCV-induced liver lesions to hepatocellular carcinoma." (PMID 41465470, 2025). "Knockdown of HOTAIR in hypoxia-treated hepatocellular carcinoma cells inhibits glycolysis via regulation of miR-130a-3p and HIF1A, a novel glycolysis mechanism in hepatocellular carcinoma." (PMID 39167430, 2024). "The latest research shows HOTAIR knockdown suppressed cell proliferation, migration and invasion, and promoted apoptosis via regulating miR-526b-3p/DHX33 axis in hepatocellular carcinoma (HCC) cells." (PMID 37576402, 2023). "In hepatocellular carcinoma (HCC), downregulation of HOTAIR weakened Taxol resistance through the Wnt/β-catenin and Akt phosphorylation pathways via antagonizing miR-34a." (PMID 36100611, 2022). "Some of these lncRNAs include HOTAIR, HULC, PTV1, and MALAT1, which are also involved in the regulation of autophagy in hepatoma cells." (PMID 32473641, 2020). "Meanwhile, HOTAIR has also been shown to enhance cell autophagy through up-regulation of ATG3 and ATG7 in hepatocellular carcinoma." (PMID 32396526, 2020). "Long noncoding RNAs (lncRNAs), such as LINC00462, HOTAIR, and MALAT1, are significantly upregulated in hepatocellular carcinoma (HCC) tissues." (PMID 32554864, 2020). "Recently, the mechanism and function of several lncRNAs such as HOTAIR, HULC, and MALAT1 were reported in hepatic carcinoma resulting in construction of lncRNA regulatory networks in hepatic carcinoma." (PMID 28938565, 2017). "For examples, HOTAIR could promote migration and invasion of hepatocellular carcinoma (HCC) cells and promotes human liver cancer stem cell malignant growth." (PMID 27167190, 2016). "HOTAIR could promote migration and invasion of hepatocellular carcinoma (HCC) cells by inhibiting RBM38." (PMID 27367027, 2016). "In hepatocellular carcinoma (HCC) and HCC patients with liver transplantation, the levels of HOTAIR compared with normal liver tissue are elevated." (PMID 23443164, 2013). "In addition, it was observed that the high expression level of HOTAIR in hepatocellular carcinoma could be a candidate biomarker for predicting tumor recurrence in hepatocellular carcinoma patients who have undergone liver transplant therapy and might be a potential therapeutic target." (PMID 22613733, 2012). "In addition, lncRNA downregulated in hepatocellular carcinoma (DRHC), which is a key tumor-suppressor IncRNA in TNBC, negatively regulates the expression of HOTAIR and inhibits the proliferation of TNBC cells." (PMID 36997931, 2023). "Higher HOTAIR expression is also observed in hepatocellular carcinoma (HCC) tissues compared to adjacent non-tumor tissues, and again expression level is associated with lymphatic metastasis." (PMID 27686732, 2016). "HOTAIR is also overexpressed in HCC and hepatoma cell lines." (PMID 25119862, 2014). "Knockdown of HOTAIR down-regulated proteins related to cell motility and metastasis, such as matrix metalloproteinase (MMP)-9 and vascular endothelial growth factor (VEGF), and decreased proliferation of Bel7402, a hepatoma cell line." (PMID 25334066, 2014).
hepatocellular carcinoma (continued). "Overexpression of HOTAIR in hepatocellular carcinoma (HCC) can also promote the invasion and migration of HCC by enhancing the EMT regulatory process, in which HOTAIR upregulates ZEB gene expression by sponging miR-23b-3p." (PMID 35819532, 2022). "For example, HOTAIR, a 2,158 bp lncRNA, is more highly expressed in HCC tissues than in non-tumor tissues; promotes cell proliferation, autophagy, and invasion; and reduces the response of hepatoma cells to the apoptosis stimulator TNF-α and chemotherapeutic drugs." (PMID 34277410, 2021). "Three lncRNAs, H19, HOTAIR and lncRNA highly upregulated in liver cancer (HULC), were found overexpression in human hepatocellular carcinomas (HCC)." (PMID 24063685, 2013). "In primary hepatocellular carcinoma (HCC), HOTAIR overexpression is not observed in every cancer patient." (PMID 25334066, 2014).